LCP1 (lymphocyte cytosolic protein 1)
Description:
Actin-binding protein. Plays a role in the activation of T-cells in response to costimulation through TCR/CD3 and CD2 or CD28. Modulates the cell surface expression of IL2RA/CD25 and CD69.
Synonyms: PLS2; CP64; L-PLASTIN; LC64P; HEL-S-37
Tractability: Small molecule: a structure with a bound ligand is known; it has a binding pocket of medium quality. Antibody: its Gene Ontology location is reachable by antibodies, with high confidence; UniProt places it where antibodies can reach, with medium confidence; the Human Protein Atlas places it where antibodies can reach. PROTAC: ubiquitination databases record sites on it; its protein half-life has been measured.
Gene: Protein-coding gene on chromosome 13 (46,125,920 to 46,211,871, reverse strand). Ensembl gene ENSG00000136167.
Subcellular location: Cytoplasm, cytoskeleton; Cell junction; Cell projection; Cell projection, ruffle membrane
Subcellular location (Human Protein Atlas): Plasma membrane; Actin filaments; Cytosol
Pathways (Reactome):
Immune System: Gene and protein expression by JAK-STAT signaling after Interleukin-12 stimulation
Gene Ontology:
Molecular function: actin filament binding; GTPase binding; integrin binding; actin binding; calcium ion binding
Biological process: actin filament bundle assembly; cell migration; regulation of intracellular protein transport; T cell activation involved in immune response; wound healing, spreading of cells; actin crosslink formation; cortical actin cytoskeleton organization
Cellular component: actin cytoskeleton; actin filament; actin filament bundle; anchoring junction; cytoplasm; cytosol; extracellular exosome; extracellular region; filopodium; focal adhesion; perinuclear region of cytoplasm; plasma membrane; ruffle; stress fiber; cell junction; phagocytic cup; cytoskeleton; ruffle membrane
Genetic constraint (gnomAD): Loss-of-function variants: 15 observed, 59.24 expected, observed/expected ratio (o/e) 0.25, 90% interval 0.17 to 0.39. The upper end of that interval is the gene's LOEUF score, 0.39, which puts it in group 1 of 6, group 1 being the genes least tolerant of losing a copy. Missense variants: 494 observed, 683.92 expected, observed/expected ratio (o/e) 0.72, 90% interval 0.67 to 0.78. Synonymous variants: 219 observed, 256.83 expected, observed/expected ratio (o/e) 0.85, 90% interval 0.76 to 0.95.
Homologues: Orthologues: chimpanzee LCP1 (99% identical), macaque LCP1 (99% identical), dog LCP1 (98% identical), rabbit LCP1 (98% identical), pig LCP1 (97% identical), mouse Lcp1 (97% identical), guinea pig LCP1 (97% identical), rat Lcp1 (96% identical), tropical clawed frog lcp1 (86% identical), zebrafish lcp1 (82% identical), Drosophila melanogaster Fim (53% identical), Caenorhabditis elegans plst-1 (31% identical), and 1 more. Paralogues in human: PLS3 (80% identical), PLS1 (73% identical).
Diseases named in the same sentence as LCP1 in open-access papers:
LCP1 is named in the same sentence as 85 diseases in open-access papers, as found by Europe PMC text mining. Sharing a sentence is not in itself a finding about the gene and the disease. The quoted sentences say what the papers report.
breast carcinoma (20 papers, 2010 to 2025). "Accumulating research has revealed that the upregulation of LCP1 expression is closely associated with the development of a wide range of human tumors, including colorectal cancer, prostate cancer, breast cancer, and oral cancer." (PMID 38977952, 2024). "Reportedly, CXCR7 modulates CXCR4 signaling and enhances CXCL12-induced cell migration and metastasis of breast cancer cells, and LCP1 is implicated in the CXCL12-induced migration of chronic lymphocytic leukemia cells." (PMID 26413813, 2015). "In breast cancer, phosphorylation of LCP1 at Ser5 via the PI3K/SGK cascade enhances its oncogenic activity." (PMID 41044643, 2025). "The abnormally expressed LCP1 is closely related to the stages and severity of various cancers, and LCP1 has been regarded as a potential prognostic indicator in colon and breast cancers." (PMID 36574182, 2023). "Particularly, LCP1 plays a role in the activation of T-cells and its exosomal release by breast cancer cells was found to facilitate metastatic bone osteolysis." (PMID 33182810, 2020). "We demonstrated that downregulation of LCP1 resulted in significantly reduced breast cancer cell migration and invasion, and that dual ABCE1+LCP1 knockdown further inhibits cell motility, especially invasion." (PMID 31007850, 2019). "We showed that LCP1 is downregulated in human and mouse breast cancer cell lines-both on the RNA and protein levels-in response to miR-96 overexpression." (PMID 31007850, 2019). "Together, these results suggest that the additive effect of two miR-96 gene targets, ABCE1 and LCP1, has a functional role in the downregulation of breast cancer growth, aggressiveness, and survival." (PMID 31007850, 2019). "We identified one such gene, L-Plastin (LCP1), and assessed its effect on breast cancer progression." (PMID 31007850, 2019). "In conclusion, we demonstrated that LCP1 is directly regulated by miR-96 and has an important role in controlling breast cancer cell motility." (PMID 31007850, 2019). "Additionally, among different breast cancer subtypes, the highest expression of LCP1 was observed in the basal subtype." (PMID 38977952, 2024). "Elevated LCP1 levels have been shown to correlate with increased cell migration and invasion in colorectal, oral, prostate, and cholangiocarcinoma cancers, as well as with an increased number of lung metastases in breast cancer mouse models." (PMID 31007850, 2019). "Therefore, we proceeded to explore the role of LCP1 in breast cancer metastasis formation and, especially, the additive effect of LCP1 and ABCE1 on this process." (PMID 31007850, 2019). "Indeed, AGR2, LCP1 and S100P overexpression have been previously correlated with breast cancer progression, and we now link the aberrant expression of these genes with ErbB2 expression." (PMID 20840765, 2010). "To evaluate LCP1 as a miR-96 target in vitro and in vivo, we examined its expression in 4T1, MDA-231, and HS578 breast cancer cells that overexpress miR-96 or scrambled miRNA." (PMID 31007850, 2019). "These evidences indicated that, in addition to CXCR4, the expression of CXCR7 and LCP1 was also in the downstream of GLI1 and GLI2 in breast cancer cells." (PMID 26413813, 2015). "Assuming therefore that GLI1 up-regulates a set of these CXCL12-related signaling components in breast cancer cells, we focused our study on CXCR4, CXCR7 and LCP1." (PMID 26413813, 2015). "We here present evidence that GLI1 up-regulates the expression of CXCR4, CXCR7 as well as LCP1/L-PLASTIN, an actin-binding protein crucial for CXCL12/CXCR4 signaling, in breast cancer cells." (PMID 26413813, 2015). "Moreover, compared to normal and luminal subtypes, the protein expression levels of LCP1 were also upregulated in TNBC and HER2-positive breast cancer samples." (PMID 38977952, 2024).
breast carcinoma (continued). "It was initially found to be expressed only in hematopoietic cells but recent studies demonstrated that LCP1 also occurs in many nonhematopoietic malignancies such as colon, prostate and breast cancers." (PMID 35008858, 2021). "The plastin-2 (LCP1) gene was shown to be relevant in MBC due to its FC values and its responsiveness to testosterone in androgen receptor (AR)-positive prostate and breast cancer cells." (PMID 33656060, 2021). "To examine the effect of LCP1 knock down (KD) and dual ABCE1+ LCP1 KD on cell migration, we used shRNAs to stably underexpress ABCE1, LCP1, ABCE1+ LCP1, or scrambled in HS578 human breast cancer cells and 4T1 murine breast carcinoma cells." (PMID 31007850, 2019). "Furthermore, we revealed that GLI1 up-regulated the expression of CXCR4, CXCR7, and LCP1 to enhance the CXCL12-induced ERK phosphorylation and migration of breast cancer cells." (PMID 26413813, 2015). "We identified one such gene – LCP1 – and proved its negative effect on breast cancer progression." (PMID 31007850, 2019).
prostate carcinoma (10 papers, 2012 to 2024). A carcinoma that arises from epithelial cells of the prostate gland. "Similarly, LCP1 was confirmed to promote the cell invasion and metastasis in prostate cancer cells, and the silencing experiment indicated that LCP1 might be an effective approach for tumors treatment." (PMID 36574182, 2023).
melanoma (9 papers, 2014 to 2025). A malignant, usually aggressive tumor composed of atypical, neoplastic melanocytes. "However, the expression patterns of LCP1 in other types of cancer differ; in cancers such as cholangiocarcinoma, gastric cancer, and melanoma, high expression of LCP1 is closely related to poor prognosis." (PMID 38977952, 2024). "In agreement with the differential abundance analysis, APCA+ on the cell type indicates that monocytes are characterized by high intensities of CORO1A, LCP1, TMSB4X, and RPL13, while melanoma cells are characterized by higher intensities of VIM and MCALL1." (PMID 40775377, 2025).
osteosarcoma (7 papers, 2021 to 2025). A usually aggressive malignant bone-forming mesenchymal neoplasm, predominantly affecting adolescents and young adults. "LCP1 has been reported to promote proliferation and metastasis in osteosarcoma cells via the JAK2/STAT3 pathway." (PMID 41044643, 2025). "Consistent with our findings, LCP1 has been found to promote cell migration and invasion in osteosarcoma and chondrosarcoma (bioRxiv 2023:2023.01.31.526513) cell lines." (PMID 38810090, 2024). "It has been reported that lymphocyte cytoplasmic protein 1 (LCP1) in BMSC-Exos promotes the progression of osteosarcoma through the JAK2/STAT3 pathway, suggesting that targeting LCP1 may provide a means to treat osteosarcoma." (PMID 36678850, 2023). "Recent studies on osteosarcoma involving the LCP1 gene (also known as actin-bundling protein L-plastin or LPL), have shown that the aberrant expression of LCP1 gene activates the JAK2/STAT3 signaling pathway, linking IL-6, IL-6R, and LCP1 in the context of tumor progression." (PMID 40759647, 2025).
cerebral infarction (6 papers, 2022 to 2025). An ischemic condition of the brain, producing a persistent focal neurological deficit in the area of distribution of the cerebral arteries. "Decreased lactylation of lymphocyte cytosolic protein 1 (LCP1) caused by glycolysis inhibition reduces LCP1 stability during cerebral infarction progression." (PMID 38439082, 2024). "In cerebral infarction, the lactylation level of lymphocyte cytotoxic protein 1 (LCP1) is notably increased, and the inhibition of glycolysis can reduce the lactylation level of LCP1, ultimately alleviating the progression of cerebral infarction." (PMID 40584617, 2025). "After cerebral infarction, lactate accumulates in ischemic and hypoxic tissues and induces lymphocyte cytosolic protein 1 (LCP1) lactylation, which can stabilize LCP1, thus aggravating neuron injuries and the progression of cerebral infarction." (PMID 40881348, 2025). "Furthermore, glycolysis inhibition and lactate production reduce the lactylation of lymphocyte cytosolic protein 1 (LCP1), an actin‐binding protein in cerebral infarction models, leading to LCP1 degradation, apoptosis suppression, and ultimately attenuation of CI progression." (PMID 40599233, 2025). "Down-regulation of Maclpil can inhibit the migration and phagocytosis of monocyte-macrophages by regulating LCP1, reduce the size of cerebral infarction in MCAO/R mice, improve neurobehavioral function, and reduce the infiltration of monocyte-macrophages in the cerebral infarct area." (PMID 36275741, 2022).
colon cancer (6 papers, 2004 to 2023). "On the other hand, LCP-1 polymorphism (LCP1 rs494153) may be closely associated with its over-expression leading to predict colon cancer prognosis." (PMID 28230172, 2017). "Colon cancer outcomes are associated with changes in MDSC infiltration, and therefore LCP1, ITGB2, and IKZF1 may be novel targets for immunotherapy." (PMID 36230637, 2022). "Through further experimental verification, we revealed that the expression of LCP1, ITGB2, and IKZF1 were significantly upregulated in right-sided colon cancer samples compared to that of left-sided colon cancer samples (p < 0.05)." (PMID 36230637, 2022).
lymph node metastasis (6 papers, 2017 to 2025). "Subsequently, a chi-square test analysis of 29 TNBC patients and 11 patients with benign tumors was conducted to examine the relationship between LCP1 immunohistochemical scores and age (P=0.66), stage (P=0.639), histological type (P=0.083), lymph node metastasis (P=0.715), and size (P=0.450)." (PMID 38977952, 2024). "LCP1 was correlated with lymph node metastasis and proposed as independent PC prognostic factor, while GLO1 might serve as a high-grade prostatic intraepithelial neoplasia marker and is strongly linked to early biochemical recurrence." (PMID 36818049, 2023). "LCP1 was recently found to be a regulator of OSCC progression and positively correlates with the primary tumoral size and regional lymph node metastasis." (PMID 37242569, 2023). "Three genes—ADGRE5, COTL1, and LCP1—were significantly upregulated in OSCCs with lymph node metastasis compared to those without lymphatic metastasis." (PMID 41044643, 2025).
colorectal cancer (5 papers, 2009 to 2018). A primary or metastatic malignant neoplasm that affects the colon or rectum. "Although little is known about the molecular mechanisms that regulate LCP1 transcription and translation, a variant in the promoter region of LCP1 causes a decreased risk for prostrate cancer while other variants in LCP1 are proposed as biomarkers for colorectal cancer recurrence and eQTLs." (PMID 29317542, 2018). "Up-regulation of plastin-2 occurs in various human cancers and a coding SNP in LCP1 has been correlated with gender- and tumour-stage specific prognostic significance in colorectal cancer recurrence." (PMID 26264041, 2015).
gastric cancer (5 papers, 2019 to 2025). A primary or metastatic malignant neoplasm involving the stomach. "Similarly, LCP1 has been validated as a prognostic biomarker and is linked to immune infiltrate in gastric cancer." (PMID 40740857, 2025). "In fact, LCP1 has been identified as a prognostic marker in oral, colon, kidney and gastric cancers." (PMID 38977952, 2024). "CXC chemokine receptor 4 (CXCR4), which is a prognostic marker for gastric cancer, leukemia, and other cancers, and can increase levels of its downstream molecule LCP1, is activated by the regulator GLI1." (PMID 31360146, 2019). "Additionally, LCP1 has been identified as a contributor for chidamide resistance in gastric cancer." (PMID 40740857, 2025). "Although LCP1 may play a complex role in GC, gaps remain in understanding its differential expression and functional impact based on tumour location—specifically when comparing cardia and noncardia gastric cancers, which differ in aetiology, histology, and molecular characteristics." (PMID 40999796, 2025).
periodontitis (5 papers, 2011 to 2022). An acute or chronic inflammatory process that affects the tissues that surround and support the teeth. "Plastin-2 (LCP1) regulates leukocyte adhesion to integrin and has been described among salivary proteins associated with periodontitis in patients with type 2 diabetes mellitus." (PMID 34064456, 2021). "In accordance with a previous report, myeloperoxidase, myosin 9, annexin A3, profilin-1, L-plastin (plastin-2/LCP1), S100A8, and S100A9 were detected at higher levels in chronic periodontitis patients compared to healthy individuals." (PMID 21794177, 2011).
COVID-19 (4 papers, 2022 to 2025). A disease caused by infection with severe acute respiratory syndrome coronavirus 2. "Reanalysis of single cell transcriptome data from three independent COVID-19 cohorts revealed that the LCP1 gene exhibited a significant elevated expression in monocytes in individuals infected by SARS-CoV-2 compared to healthy or convalescent donors." (PMID 40759647, 2025). "COVID-19 subsets additionally expressed LCP1, STAT5B, and ILF3, which are involved in T-cell activation and signaling." (PMID 36992700, 2023). "Furthermore, a previous proteomics study revealed the role of LCP1 in COVID-19 patients." (PMID 40759647, 2025). "From these proteins CRTAC1, IGLV3-1, HRG, HSPB1, LCP1, ITIH3, and APOA2 have all been identified as correlating with COVID-19 in other research, but to our knowledge, the rest are novel." (PMID 37308820, 2023).
kidney cancer (4 papers, 2014 to 2022). Primary or metastatic malignant neoplasm involving the kidney. "LCP1 is interesting, because as L‐plastin, it has been associated with membrane dynamics and the cytoskeleton and is an early tumor marker in kidney cancer." (PMID 36169042, 2022).
lymphoma (3 papers, 2017 to 2022). A malignant (clonal) proliferation of B- lymphocytes or T- lymphocytes which involves the lymph nodes, bone marrow and/or extranodal sites. "It was reported LCP1 was highly expressed in leukemia and lymphoma cell lines." (PMID 31360146, 2019). "The role of LCP1 and HCK in leukemia or lymphoma has been sporadically reported." (PMID 35771283, 2022).
Obesity (3 papers, 2018 to 2023). Accumulation of substantial excess body fat. "In our previous study, we reported that 14 adipocyte genes (Ccl7, Emr1, Evi2a, Gusb, H2-DMb2, Lcp1, LOC100041137, Ly9, Ptpre, Rgs1, sc1000528.1_16, Sirpa, Sfrp5, and Acacb) were associated with both advanced age and diet-induced obesity." (PMID 30282902, 2018). "The hub genes calculated by Cytoscape software are MNDA (score 320), CYBB (score 314), CD86 (score 312), FCGR2C (score 242), NCF2 (score 240), LCP2 (score 182), TLR8 (score 148), HLA-DRA (score 54), LCP1 (score 30), and PTPN22 (score 8), which are considered to be associated with obesity-related AF." (PMID 36671813, 2023).
oral cancer (3 papers, 2017 to 2025). "We recently found that LCP1 overexpression was an essential aspect of various oral cancer progressions, therefore the siLCP1 was selected this RNAi experiments." (PMID 33723306, 2021). "We recently found that LCP1 overexpression was an essential aspect of oral cancer progression." (PMID 33723306, 2021).
oral squamous cell carcinomas (3 papers, 2017 to 2023). "LCP1, a member of the actin-binding protein family of plastins is important for the activation of human peripheral blood T lymphocytes and was recently reported to be upregulated and to serve a critical role in oral squamous cell carcinomas." (PMID 30918060, 2019). "However, the functional significance of LCP1 expression in oral squamous cell carcinomas (OSCCs) for tumoral cellular proliferation and metastasis remains uncertain." (PMID 28230172, 2017). "However, little is known about the roles of LCP1 in oral squamous cell carcinomas (OSCCs)." (PMID 28230172, 2017).